GRHL2-DT (GRHL2 divergent transcript )
Synonyms: BX357664
Gene: Long non-coding RNA gene on chromosome 8 (101,460,005 to 101,493,338, reverse strand). Ensembl gene ENSG00000254024.
Diseases named in the same sentence as GRHL2-DT in open-access papers:
GRHL2-DT is named in the same sentence as 4 diseases in open-access papers, as found by Europe PMC text mining. Sharing a sentence is not in itself a finding about the gene and the disease.
GRHL2-DT shares sentences with these, for which no sentence is quoted: bladder tumor (1 paper); cancer (1); prostate carcinoma (1); tumor (1).